METTL14 (methyltransferase 14, N6-adenosine-methyltransferase non-catalytic subunit)
Diseases named in the same sentence as METTL14 in open-access papers (continued):
Sharing a sentence is not in itself a finding about the gene and the disease.
endometrial cancer (30 papers, 2019 to 2025). Primary or metastatic malignant neoplasm involving the endometrium (mucous membrane that lines the endometrial cavity). "Mutations in METTL14 that cause an inefficient RNA-binding domain are found in endometrial cancers, and the mutated form of the enzyme shows partially reduced activity." (PMID 36894952, 2023). "R298 of METTL14 is located close to the METTL3/METTL14 junction and catalytic site, and this mutation is frequently found in human endometrial cancer, suggesting the biological relevance of a mutation in the inactive activator of the METTL3/METTL14 complex." (PMID 36889590, 2023). "YTHDC1 and METTL14, in particular, have been identified as possible endometrial carcinoma diagnostic and prognostic indicators." (PMID 35159736, 2022). "For example, in endometrial cancer, 70% of tumours exhibit a reduction in m6A levels, either through METTL14 mutations or downregulation of METTL3 expression." (PMID 33461542, 2021). "Increased Akt activation with decreased m6A methylation of the target transcripts due to mutation in METTL14 or METTL3 downregulation contributed to endometrial cancer progression." (PMID 33814008, 2021). "In endometrial cancer, METTL14 is deviancy due to mutation, which promotes cell proliferation by altering AKT signaling." (PMID 33552994, 2020). "In endometrial cancer, METTL14 mutation or METTL3 down-regulation leads to a decrease of mTOR m6A levels, which is a regulator of oncogene AKT." (PMID 32998774, 2020). "For example, decreased METTL3 expression or METTL14 mutation in endometrial cancer reduces the m6A modification of AKT pathway-related genes, resulting in the activation of the AKT signaling pathway and contributing to tumorigenesis." (PMID 31722709, 2019). "For example, hotspot R298P mutations occurring in the methylation enzyme METTL14 may be involved in the proliferation of endometrial cancer cells by affecting the activity of AKT pathways, such as the AKT regulators PHLPP2 and mTORC2." (PMID 36894952, 2023). "Recently, it is found that mutation of METTL14 in endometrial cancer cells could down regulate m6A mRNA methylation and enhance proliferation and tumorigenicity by regulating AKT activity." (PMID 33430867, 2021). "In endometrial cancer, METTL14 acts as a tumor suppressor, and its expression is significantly diminished and is positively associated with tumor aggressiveness and metastatic potential." (PMID 40746896, 2025). "In patients with endometrial cancer, METTL14 levels are decreased in tumour samples, promoting the proliferation of endometrial cancer cells." (PMID 40356909, 2025). "The differences were likely due to a METTL14 mutation or reduced expression of METTL3, which promotes cell proliferation and the tumorigenicity of endometrial cancer through the activation of AKT signaling pathway." (PMID 35280730, 2022). "In endometrial cancer, 70% of tumors result in reduced m6A levels through the downregulation of METTL3 expression or METTL14 mutation." (PMID 36360287, 2022). "For example, endometrial cancer is associated with a reduced level of m6A mRNA methylation because of decreased expression of METTL3 and METTL14 and reduced m6A methylation promotes the proliferation of endometrial cancer cell." (PMID 34149801, 2021). "Reductions in m6A methylation induced by decreased METTL3 and mutation in METTL14 activate the phosphoinositide 3 kinase/protein kinase B (PI3K/AKT) pathway, promoting proliferation and tumorigenicity of endometrial cancer." (PMID 34149936, 2021). "In particular, ZC3H13, YTHDC1, and METTL14 were identified as potential markers for endometrial cancer diagnosis and prognosis." (PMID 34230220, 2021). "In endometrial cancer, METTL14 overexpression promotes ferroptosis by destabilizing GPX4 mRNA." (PMID 40271153, 2025).
endometrial cancer (continued). "The loss of METTL3 and METTL14 complexes can upregulate the expression of AKT pathway members and lead to increased cell proliferation, which in turn exhibits tumor suppressor functions in endometrial cancer." (PMID 36360287, 2022). "Recently, decreased m6A RNA methylation level caused by METTL14 R298 mutation or decreased METTL3 expression has been reported to promote tumorigenicity and cell proliferation via activation of AKT signaling pathway in endometrial cancer." (PMID 34149936, 2021). "However, METTL14 plays a carcinogenic role in endometrial cancer by regulating AKT activation through m6A modifications." (PMID 33237039, 2020). "In endometrial cancer, PRMT3-mediated arginine methylation of METTL14 promotes tumor progression and treatment resistance." (PMID 40271153, 2025). "In endometrial cancer, PRMT3 interacts with the Arg418 residue of METTL14 and enhances METTL14’s m6A catalytic activity via methylation, thereby regulating ferroptosis-related genes." (PMID 41583428, 2025). "In endometrial carcinoma, PRMT3 drives malignant progression by methylating METTL14, reducing m6A modification of GPX4." (PMID 40050608, 2025). "In endometrial cancer, METTL3 and METTL14 exhibit a tumor suppressor function." (PMID 38343637, 2024). "Interestingly, although METTL3 and METTL14 seem to play completely opposite roles in HCC progression, which may not be the case in other tumors, such as downregulated METTL3 expression detected in approximately 70% of endometrial cancers, which may be related to tumor heterogeneity." (PMID 35223847, 2022).
atherosclerosis (29 papers, 2020 to 2026). A disease characterized by the build-up of fatty material and calcium deposition in the arterial wall resulting in partial or complete occlusion of the arterial lumen. "It has also been shown that METTL14 promotes inflammatory responses in atherosclerosis-associated macrophages via NF-κB/IL-6 signaling." (PMID 37441706, 2023). "Taken together, these results prompted us to explore the consequences of increased Mettl14 in macrophages caused by atherosclerosis." (PMID 35598196, 2022). "METTL14 promotes inflammatory responses in atherosclerosis-associated macrophages through NF-κB/IL-6 signaling pathway and also increases m6A modification of forkhead box O1 (FOXO1), thereby increasing adhesion molecule expression, mediating endothelialmonocyte adhesione." (PMID 40662138, 2025). "Together, these findings uncover a novel function of the METTL14 N-terminal in the regulation of atherosclerosis and highlighting its potential as a protein-based therapeutic strategy for atherosclerosis intervention." (PMID 41510160, 2026). "Third, although our in vitro and in vivo experiments demonstrate that sno-circCNOT1 promotes atherosclerosis progression through the LMNA/METTL14 /NLRP3 axis, its clinical significance remains to be fully elucidated." (PMID 41510160, 2026). "METTL14, as another member of the m6A methyltransferase family, can exacerbate the development of atherosclerosis by promoting inflammation in ECs." (PMID 40861271, 2025). "Overexpression of METTL14 has also been shown to aggravate other inflammatory diseases through m6A modification, such as atherosclerosis, podocyte inflammatory injury, and rheumatoid arthritis." (PMID 39319864, 2025). "It is found that m6A-related enzymes such as methyltransferase-like 14 (METTL14) were upregulated in the aortic intima of patients with atherosclerosis." (PMID 40861271, 2025). "It was found that the knockdown of METTL14 significantly inhibited ECs and atherosclerotic plaque formation, suggesting the therapeutic potential of METTL14 in atherosclerosis." (PMID 40662138, 2025). "MEHP inhibits SR-B1 expression by decreasing METTL14 expression, suppressing cholesterol efflux from macrophages, and accelerating atherosclerosis." (PMID 40066451, 2025). "Our results showed that the expression levels of m6A, METTL3, and METTL14 were significantly increased in cell and animal models of atherosclerosis." (PMID 39432244, 2024). "As reported in a meta‐analysis, the expression levels of METTL3 and METTL14 were increased in vascular endothelial cell, macrophage, and smooth muscle cell models of atherosclerosis, consistent with our study findings." (PMID 39432244, 2024). "The results showed that m6A, METTL3, and METTL14 expression levels in the atherosclerosis experimental models were much higher than those in the control models." (PMID 39432244, 2024). "First, we explored the expression of key writer proteins METTL3 and METTL14 in animal and cell models of atherosclerosis during m6A modification." (PMID 39432244, 2024). "Here, we found that the Mettl14 “writer” can regulate the inflammatory state of macrophages in atherosclerosis." (PMID 35598196, 2022). "Given that Mettl14 regulates the functions of macrophages in vitro, we further assessed the effect of Mettl14 on atherosclerosis progression in vivo." (PMID 35598196, 2022). "The m6A writer Mettl14 plays a critical role in the regulation of m6A modification in macrophages in atherosclerosis." (PMID 35598196, 2022). "In vivo, Mettl14 gene knockout in mice significantly reduced the development of atherosclerosis by decreasing the inflammatory response of macrophages." (PMID 35598196, 2022). "In this study, we first reported that Mettl14 regulated the inflammatory state of macrophages in atherosclerosis." (PMID 35598196, 2022). "In conclusion, the results suggest that Mettl14 can regulate the function of macrophages in atherosclerosis via Myd88/IL-6 in vivo." (PMID 35598196, 2022).
atherosclerosis (continued). "At least, these data revealed that in atherosclerosis and other CVDs, m6A writer METTL14 is upregulated and eraser FTO is downregulated." (PMID 35211628, 2022). "These transfected cells were then used to evaluate the relationship between p65 and METTL14 and its effects on viability and apoptosis in the atherosclerosis cell model." (PMID 35543357, 2022). "METTL14 also promotes endothelial inflammation and atherosclerosis via inducing FOXO1 m6A modifications." (PMID 35013140, 2022). "The effect of METTL14 on atherosclerosis development in vivo was verified using METTL14 knockout mice." (PMID 32802173, 2020). "More importantly, we found that METTL14 knockout significantly inhibited atherosclerosis development, demonstrating the potential of METTL14 in the treatment of atherosclerosis and related disorders." (PMID 32802173, 2020). "This is consistent with our findings, which demonstrated that the expression of FOXO1 in METTL14 knockdown mice was reduced and the development of atherosclerosis was significantly inhibited." (PMID 32802173, 2020). "Decreased expression of METTL14 can inhibit endothelial inflammation and atherosclerosis development." (PMID 32802173, 2020). "In the context of aneurysms, similar to how METTL14 promotes DGCR8-mediated processing of pri-miR-19a in atherosclerosis, METTL3-dependent m6A methylation promotes primary miR-34a maturation through DGCR8, leading to decreased SIRT1 expression and an aggravated aneurysm formation." (PMID 40005339, 2025). "Knockdown of METTL14 may enhance vascular repair function by reducing calcification, presenting a potential therapeutic approach for atherosclerosis and valvular diseases." (PMID 40005339, 2025). "For example, in atherosclerosis, myeloid differentiation factor 88 (My88) expression is induced by LPS METTL14 upregulates the My88 phosphorylation level and exacerbates vascular endothelial inflammation, suggesting that METTL14-related m6A is involved in atherosclerotic inflammation." (PMID 38562618, 2024). "Furthermore, another m6A writer, METTL14, was reported to increase the translation of Foxo1 and aggravated endothelial inflammation and atherosclerosis." (PMID 37486903, 2023). "METTL14 deletion reduces the m6A methylation modification in atherosclerosis." (PMID 35013140, 2022). "Knockout out of METTL14 significantly inhibits endothelial inflammation and the formation of atherosclerotic plaques, demonstrating the therapeutic potential of METTL14 in the treatment of atherosclerosis." (PMID 35406663, 2022). "Our data indicate that Mettl14 may be a promising therapeutic target of macrophages in the treatment of atherosclerosis." (PMID 35598196, 2022). "It is possible, therefore, that Mettl14 has a pivotal role in macrophages in atherosclerosis." (PMID 35598196, 2022). "Knocking down METTL14 could inhibit the development of atherosclerosis in high-fat diet-treated APOE−/− mice." (PMID 35543357, 2022). "Moreover, since METTL14+/- mice showed expression of METTL14 in endothelial cells, the role of METTL14 in atherosclerosis development needs further clarification." (PMID 32802173, 2020). "To determine whether METTL14 was involved in atherosclerosis, we detected METTL14 expression in atherosclerotic samples from APOE-knockout mice." (PMID 32802173, 2020). "Similarly, METTL14 also plays a vital role in the pathogenesis of atherosclerosis." (PMID 40662138, 2025). "METTL14 is documented to methylate pri-miR-19a and promote the processing of the mature miR-19a, stimulating the proliferation and invasion of atherosclerotic vascular endothelial cells, indicating that the METTL14/m6A/miR-19a axis may represent a novel target for anti-atherosclerosis treatment." (PMID 37441706, 2023). "In fact, the METTL14 could act as a potential therapeutic target for atherosclerosis." (PMID 36178367, 2022). "Therefore, the METTL14/M6A/mir-19a signaling pathway could be a new therapeutic target for atherosclerosis." (PMID 36178367, 2022).
atherosclerosis (continued). "METTL14 may be a new target for the treatment of atherosclerosis." (PMID 34489709, 2021). "METTL14 may be a potential target for clinical treatment of atherosclerosis." (PMID 34489709, 2021). "Hence, our results confirmed that METTL14 may inhibit atherosclerosis development by regulating FOXO1 expression in mice." (PMID 32802173, 2020). "In conclusion, our findings demonstrate that shear-sensitive sno-circCNOT1 promotes endothelial pyroptosis and inflammation via the LMNA/METTL14/NLRP3 axis, thereby accelerating atherosclerosis progression." (PMID 41510160, 2026). "Studies have demonstrated that in human umbilical vein endothelial cells, METTL3 and METTL14 can upregulate p65 expression, leading to decreased levels of BCL-2 and exacerbated atherosclerosis." (PMID 41373022, 2025). "In the aortas of atherosclerosis mice, overall m6A levels were significantly elevated compared with controls (p < .05), with METTL3 and METTL14 mRNA and protein levels notably increased (p < .05)." (PMID 39432244, 2024). "Taken together, our data demonstrate that Mettl14 plays a vital role in macrophage inflammation in atherosclerosis via the NF-κB/IL-6 signaling pathway, suggesting that Mettl14 may be a promising therapeutic target for the clinical treatment of atherosclerosis." (PMID 35598196, 2022). "In conclusion, METTL14 promoted the FOXO1 expression by reinforcing the m6A modification and inducing the endothelial inflammatory response and atherosclerosis plaque formation." (PMID 36178367, 2022). "The knockdown of METTL14 led to the inhibition of the TNF-α-induced cell senescence, endothelial inflammation, and atherosclerosis development." (PMID 36052084, 2022). "In addition, METTL3/METTL14 and m6A methylation have been reported to play roles in other diseases such as heart failure, viral infection, type 2 diabetes, cardiac remodeling, atherosclerosis, congenital heart disease, inflammation, obesity, insulin resistance, adipogenesis, and hypertension." (PMID 35211628, 2022). "Therefore, METTL14 may serve as a potential target for the clinical treatment of atherosclerosis." (PMID 32802173, 2020). "UCHL5 modified by METTL14/YTHDF1 axis could facilitate the inflammation and vascular remodeling in atherosclerosis by activating the NLRP3 inflammasome." (PMID 37441706, 2023). "Interacting with FOXO1, METTL14 acts directly on the promoter regions of ICAM-1 and VCAM-1 to upregulate their transcription, thereby mediating the inflammatory response of endothelial cells in atherosclerosis." (PMID 36482903, 2022). "Another m6A writer, METTL14, has been shown to interact with FOXO1 and act directly on the promoter regions of VCAM-1 and ICAM-1, which enhanced the binding of monocytes to endothelial cells during atherosclerosis." (PMID 34869371, 2021). "Besides, METTL14 interacted with FOXO1 and acted directly on the promoter regions of VCAM-1 and ICAM-1, which enhanced monocyte binding to endothelial cells during atherosclerosis." (PMID 34869371, 2021). "Our findings confirmed that METTL14 can enhance its translation by increasing m6A modification on FOXO1, thereby increasing adhesion molecule expression, mediating endothelial-monocyte adhesion, and participating in atherosclerosis development." (PMID 32802173, 2020). "A recent study found that exercise-induced significant down-regulation of m6A modification and METTL14, which bind to the m6A site of nuclear paraspeckle assembly transcript 1 (NEAT1) and decrease NEAT1 expression, thereby mitigating endothelial cell pyroptosis and atherosclerosis." (PMID 40662138, 2025). "The RT‐qPCR and western blotting results showed that both mRNA and protein levels of METTL3 and METTL14 in the aortas of mice in the atherosclerosis group were notably increased compared with mRNA and protein levels of METTL3 and METTL14 in the Control group (p < .05)." (PMID 39432244, 2024). "However, the function of Mettl14 in macrophages in atherosclerosis has not been reported." (PMID 35598196, 2022).